GTF2IRD2P1 (GTF2I repeat domain containing 2 pseudogene 1)
Synonyms: GTF2IRD2P
Gene: Transcribed unprocessed pseudogene on chromosome 7 (73,243,271 to 73,280,119, reverse strand). Ensembl gene ENSG00000214544.
Diseases named in the same sentence as GTF2IRD2P1 in open-access papers:
GTF2IRD2P1 is named in the same sentence as 4 diseases in open-access papers, as found by Europe PMC text mining. Sharing a sentence is not in itself a finding about the gene and the disease. The quoted sentences say what the papers report.
bladder cancer (1 paper, 2022). "The CCK8 assay and flow cytometry were used to detect the lncRNA GTF2IRD2P1 function on the proliferation of bladder cancer cells." (PMID 35433119, 2022). "GTF2IRD2P1 expression was found to be lower in both human bladder cancer tissues and cell lines (UM-UC-3, RT4, and 5637), and elevated in T24 compared to the corresponding normal controls." (PMID 35433119, 2022). "The impact of GTF2IRD2P1 on the biological function and clinical relevance in bladder cancer is largely unknown." (PMID 35433119, 2022).
tumor (2 papers, 2021 to 2022). "Box plot analysis showed that the expression level of GTF2IRD2P1 was significantly lower in tumor tissues than in normal tissues adjacent to cancerous tissues." (PMID 35433119, 2022).
cancer (1 paper, 2022). A tumor composed of atypical neoplastic, often pleomorphic cells that invade other tissues. "The results showed that the expression of GTF2IRD2P1 in BCa tissues was significantly lower than that in normal tissues adjacent to cancer." (PMID 35433119, 2022). "However, the role of lncRNA GTF2IRD2P1 has not been well studied in cancer." (PMID 35433119, 2022).
GTF2IRD2P1 also shares sentences with these, for which no sentence is quoted: oral cancer (1 paper).